CXCR4 (C-X-C motif chemokine receptor 4)
Diseases named in the same sentence as CXCR4 in open-access papers (continued):
Sharing a sentence is not in itself a finding about the gene and the disease.
breast carcinoma (continued). "Furthermore, recent research has demonstrated that CXCR4 is critical for maintaining breast cancer stemness and plays a role in resistance to CDK4/6 inhibitors through the activation of the WNT5A/β-catenin signaling pathway." (PMID 40362664, 2025). "Breast cancer cells with a high level of CXCR4 are subject to enhanced cell migration." (PMID 40548301, 2025). "In this prospective cross-sectional study, fifty-one patients with breast cancer aged 36–81 (median (Q1-Q3) 51 (42.5–63)), n = 47 (92%) with initially diagnosed and n = 4 (8%) patients with recurrent breast cancer, underwent CXCR4-targeted PET imaging using 68Ga-Pentixafor." (PMID 40075611, 2025). "Interestingly, CXCR4 has been identified in at least 23 different cancer types, including breast cancer." (PMID 40362664, 2025). "Thus, CXCR4 inhibitors have the potential for the treatment of breast cancer, particularly TNBC, as they have a more avid concentration of 68Ga-Pentixafor." (PMID 40075611, 2025). "Pancreatic and breast cancer models have also shown improvement after CXCR4 blockade." (PMID 40581668, 2025). "A meta-analysis showed that CXCR4 is an efficient prognostic factor for breast cancer." (PMID 41348904, 2025). "Preclinical evidence (murine 4T1/4T07 breast cancer models) demonstrates that IF reduces splenic accumulation of granulocytic MDSCs (CD11b+ CD33+ HLA-DR−/low CD15+) via CXCR4 (C-X-C chemokine receptor type 4) downregulation and metabolic stress-induced apoptosis." (PMID 41008741, 2025). "The observed linear correlation between Hg bioaccumulation in breast cancer tissues and CXCR4 expression suggests a potential mechanism through which this toxic metal may contribute to breast cancer progression." (PMID 40362664, 2025). "Our findings on JUNB and CXCR4 verify our prior studies on breast cancer‐derived CTCs and DTCs." (PMID 39575761, 2025). "Knocking out CXCR4 in mice delayed and regressed the growth of primary tumours, as well as preventing metastasis, showing its key role in the growth of primary tumours as well as metastasis of breast cancers." (PMID 39982274, 2025). "Previous studies proposed that it might be because HIV could bind to the chemokine receptor CXCR4 expressed by breast cancer cells, resulting in apoptosis." (PMID 40437996, 2025). "In addition, in patients with pretreated, relapsed metastatic HER2-negative breast cancer, the new CXCR4 antagonist balixafortide (POL6326, NCT01837095, phase 1) was evaluated in combination with eribulin." (PMID 40584290, 2025). "The application of omics technologies, such as WGS and RNA-seq in the context of a tumor-informed knowledge approach, allowed us to uncover a specific positive correlation between the accumulated amount of Hg in breast cancer tissues and the expression of CXCR4." (PMID 40362664, 2025). "It was shown that breast cancer cells express CXCR4 abundantly." (PMID 40969301, 2025). "Therefore, CXCR4 can serve as a specific biomarker for the early detection and treatment of breast cancer." (PMID 40175784, 2025). "In breast cancer, relatively high levels of BACH1 cause increased migration and invasion, intravasation, and in vivo metastasis by upregulating the transcriptional expression of matrix metalloproteinase 9 (MMP9) and C-X-C chemokine receptor type 4 (CXCR4)." (PMID 40710214, 2025). "HIF also induces high CXCL12/CXCR4 responsible for breast cancer progression and metastasis." (PMID 40076892, 2025). "Furthermore, CXCR4 has been identified as a prognostic marker for various types of cancer, including leukaemia, breast cancer and prostate cancer." (PMID 40342960, 2025). "Also, the expression of CXCR-4 was seen higher in TNBC subtype as compared to the other subtypes of breast cancer." (PMID 41348904, 2025). "Interestingly, several previous studies reported CXCR4 as one of the key receptors on the cell membrane that controlled breast cancer cell migration." (PMID 40548301, 2025).
breast carcinoma (continued). "Several CXCR4 antagonists have been studied in breast cancer models with encouraging outcomes." (PMID 40075611, 2025). "Blocking the CXCL12/CXCR4 pathway may suppress the growth of breast cancer cells by reducing the expression of proteins that facilitate the G2-M phase transition (PLK1, Myt1, and cyclin B1), and then disrupting mitotic processes." (PMID 39703847, 2024). "IL-1 reduces the expression of CXCR4 in breast cancer cells." (PMID 38956273, 2024). "In breast cancer, loss of SLIT/ROBO signaling may decrease the phosphorylation of downstream CXCL12/CXCR4 molecules, increase GSK-3β phosphorylation, and influence the expression and distribution of β-catenin." (PMID 39479352, 2024). "In addition, CXCR4 and JUNB have been associated with poorer overall survival (OS) of early-stage breast cancer patients and lower progression-free (PFS) and overall survival of NSCLC patients." (PMID 38727318, 2024). "Furthermore, in various tumors, including lung cancer, breast cancer, and colorectal cancer, the activation of the CXCL12/CXCR4/ACKR3 signaling axis has been associated with STAT3 pathway activation." (PMID 38920657, 2024). "As such, we identified an SDF-1/CXCR4/MDM2/MDM4 signal transduction axis that we speculate participates in driving breast cancer metastasis." (PMID 39766093, 2024). "Besides, the opposite effects of GRK3 on the CXCR4-triggered metastatic progression of breast cancer is needed to be further validated in the GRK6-promoted TNBC metastasis." (PMID 39741338, 2024). "Similarly in breast cancer, CXCR4 was shown to maintain a tamoxifen-resistant CSC population in MCF-7 cells." (PMID 38612911, 2024). "Our findings could potentially be extrapolated to other hematological malignancies and solid tumors where the SDF1/CXCR4 axis plays a role in disease progression and metastasis, such as lymphomas, multiple myeloma, and breast cancer." (PMID 39871937, 2024). "Interestingly, our analysis has revealed an association between higher CXCR4 expression and improved overall survival in HER2 breast cancer patients." (PMID 39682150, 2024). "In early breast cancer, CXCR4 was expressed in 12% of 794 primary tumors." (PMID 39001456, 2024). "Numerous studies demonstrate CXCR4 antagonists can hinder breast cancer metastasis." (PMID 38553476, 2024). "For instance, in breast cancer, the chemokine receptor CXCR4 is overexpressed and its natural ligand, CXCL12, was shown to be highly secreted near the organs that are the metastatic destination of the tumor cells, indicative of a key role in metastatic colonization." (PMID 39698539, 2024). "In breast cancer the CXCR4 mRNA promotes metastasis not only through its protein, the CXCR4 chemokine receptor, but also through the CXCR4 3′UTR that sponges the tumor-suppressive miR-146a, thus leading to the upregulation of TRAF6 and EGFR, two oncoproteins that activate the NF-κB pathway." (PMID 39054345, 2024). "Interestingly, blocking CXCR4 by AMD3100 increased T-cell infiltration in mouse models of breast cancer with high efficacy when combined with anti-PD-1 and anti-CTLA-4 treatments." (PMID 39596815, 2024). "C-X-C chemokine receptor 4 (CXCR4) is an important member of CXC chemokine receptor family, which is identified as a cell surface biomarker associated with the multiple malignant tumors, such as breast cancer and glioblastoma." (PMID 38982161, 2024). "In the present study, we show that HRH1 is the major histamine receptor highly expressed in many cancer cell lines and cancer tissues and that coexpression of CXCR4 and HRH1 is associated with lower survival in breast cancer by analyzing publicly available RNA-seq databases." (PMID 36732336, 2023).
breast carcinoma (continued). "The NF-κB signaling pathway is downstream of the CXCL12/CXCR4 axis, and its activation contributes to cancer cell survival and invasion in various types of cancer, including prostate, pancreatic, lung, and breast cancer." (PMID 38004606, 2023). "Given the minor structural differences between γ-mangostin and α-mangostin, this study hypothesized that these compounds might have a similar effect on inhibiting breast cancer cell migration, particularly regarding ROS level and CXCR4 expression." (PMID 38655233, 2023). "Using a panel of cell lines and patient breast cancer samples, we confirmed CXCR4 drives trastuzumab resistance in HER2+ breast cancer and further demonstrated the increased CXCR4 expression in trastuzumab-resistant cells is associated with cell cycle progression with a peak in the G2/M phases." (PMID 37280713, 2023). "This may be because CXCR4 mainly mediated breast cancer invasion, while CXCR7 inhibited invasion but promoted primary breast tumor growth through angiogenesis." (PMID 37497001, 2023). "CXCR4 inhibition by AMD3100 also canceled the KR-induced cell proliferation in breast cancer cells." (PMID 37760498, 2023). "68Ga-Pentixafor PET/CT may have a role in prognostication of breast cancer patients and in selecting potential candidates for therapies targeting CXCR4." (PMID 36832085, 2023). "Regarding the pleiotropic effects of DPP-4 inhibitors on cancer biology, we have previously shown that DPP-4 suppression accelerates breast cancer metastasis by inducing EMT through C-X-C motif chemokine 12 (CXCL12)/C-X-C receptor 4 (CXCR4)-mediated mTOR activation." (PMID 37760498, 2023). "Interestingly, E2 treatment alone enhanced the expression of CXCR4 in ERα-positive breast cancer cell lines." (PMID 37550554, 2023). "Among breast cancer cell lines, CXCR4 was more highly expressed by bone metastatic cells." (PMID 37025604, 2023). "The CXCR4 inhibitor treatment decreased the KR-induced gene expression profile and breast cancer progression when compared to that of the KR alone group, suggesting that mTOR pathway activation is relevant for DPP-4 inhibitor-mediated breast cancer progression." (PMID 37760498, 2023). "CXCR-4 has been identified as a potential target for breast cancer treatment." (PMID 37781195, 2023). "Therefore, we investigated the role of curcumin in ameliorating this complicated microenvironment of breast cancer by modulating the CXCL12/CXCR4 axis." (PMID 38004606, 2023). "Thus, NF-κB regulates the motility of breast cancer cells by directly upregulating the expression of CXCR4, a receptor of the SDF-1α." (PMID 36701089, 2023). "Furthermore, the C-X-C chemokine receptor type 4 (CXCR-4) was found to be upregulated on breast cancer CTCs, suggesting a potential role in regulating immune cell recruitment and function in the tumor microenvironment during treatment." (PMID 38077355, 2023). "We previously reported that CXCR4 is involved as a driver of trastuzumab resistance in HER2 + breast cancer cells with an unknown mechanism." (PMID 37280713, 2023). "In a cell binding assay, they found [64Cu]AMD3100 could bind specifically to glioblastoma cell lines (U87-stb-CXCR4) and breast cancer cell lines (DU4475) with high CXCR4 expression levels." (PMID 37375261, 2023). "In addition, CXCR7 on the surface of breast cancer cells reduced CXCR4 signaling by internalizing and degrading CXCL12." (PMID 37497001, 2023). "The measured affinity constant was 2.94 ± 0.36 μM, indicating that SI might be a potential CXCR4 antagonist that can inhibit the CXCR4-mediated migration of human breast cancer cells." (PMID 37110869, 2023). "This high expression level of both JUNB and CXCR4 was also observed in our previous studies for metastatic breast cancer patients’ CTCs (JUNB: 65% and CXCR4: 90% in patients’ cohort) and for DTCs from the bone marrow of early breast cancer patients (JUNB: 95% and CXCR4: 92% in patients’ cohort)." (PMID 36612166, 2022).
breast carcinoma (continued). "Taken together, we assume that the different patterns of CXCR4 expression determine which tissue is to be metastasized, suggesting that CXCR4 could be a prognostic biomarker for metastasis classification in breast cancer." (PMID 35045088, 2022). "Studies have revealed that CXCR4 is essential for the in vivo proliferation or survival of breast cancer cells, and its suppression may improve treatment response in patients with primary or metastatic breast cancer." (PMID 35903297, 2022). "ENTREP downregulation attenuates CXCR4 desensitization, thereby promoting breast cancer stemness." (PMID 34927784, 2022). "In vitro experiments confirmed that FPP@MNPs could be used to knockdown CXCR4 expression in breast cancer cells." (PMID 35630915, 2022). "Meanwhile, KLF5 could upregulated CXCR4 transcriptionally to accelerate epithelial and mesenchymal transition of breast cancer." (PMID 36224562, 2022). "A Dubrovska and his colleagues reported that CXCR4 activation could maintain the stem cell population in tamoxifen-resistant breast cancer cells through AhR signaling." (PMID 35831824, 2022). "A meta‐analysis demonstrated the clinically significant correlation between CXCR4 overexpression and poor prognosis of breast cancer patients as well as patients with many other malignancies, including hematological, colorectal, esophageal, head and neck, lung, and gynecologic malignancies." (PMID 34927784, 2022). "Also, it facilitates lymph node metastases of breast cancer via activating C-X-C chemokine receptor type 4 (CXCR4)/stromal cell-derived factor-1α (SDF-1α) as well as triggering cellular migration and invasion." (PMID 35910032, 2022). "Moreover, the authors discovered that the expression of CXCR4 gene is overexpressed compared to breast cancer lung metastasis cells, with CXCR4 interacting with CXCL12 to induce breast cancer cell migration." (PMID 35884845, 2022). "However, and very importantly, when agonists for both CXCR4 and CB2 receptors are administered simultaneously, heteromers are formed, and CXCR4-mediated cell migration of breast cancer cells is reduced relative to CXCR4 activation alone." (PMID 35328467, 2022). "The complex biology of CXCR4 in breast cancer warrants further studies." (PMID 35565232, 2022). "Thus, breast cancer cells with high levels of CXCR4 have a marked tendency to migrate to the sites rich in CXCL12, including bone marrow." (PMID 35236304, 2022). "This must necessarily lead to an organotropism; e.g., breast cancer cells express high levels of CXCR4 and CCR7, which are responsible for the metastasis formation in LN, lung, liver, and KM, as these organs are rich in corresponding ligands CXCL12 and CCL21 [Chambers3471]." (PMID 35326690, 2022). "Since CXCR4 signaling mechanistically drives ER-positive breast cancers to metastatic and endocrine therapy-resistant phenotypes, PET imaging with [68Ga]Pentixafor might play a role in providing spatiotemporal information over the course of endocrine therapy." (PMID 35565232, 2022). "Collectively, these results and the significant correlation of FAM189A2 downregulation with the poor long‐term prognosis of breast cancer patients illustrate that FAM189A2 is a new activator for ITCH that impacts the biology of cancer cells by regulating the CXCR4 desensitization process." (PMID 34927784, 2022). "Activation of SDF-1/CXCR4 signalling may increase the phosphorylation of 60 proteins associated with the migration and invasion of CD44+CD24− CSCs in breast cancer." (PMID 35563449, 2022). "Due to the heterogeneous accumulation of the CXCR4-targeted tracer and the small patient population, the [68Ga]Pentixafor study failed to clearly demonstrate its usefulness for cancer prediction, prognosis, or tumor grade of breast cancer." (PMID 35565232, 2022). "CXCR4 is a G-protein-coupled receptor highly expressed in breast cancer cells." (PMID 35754051, 2022).
breast carcinoma (continued). "A large number of studies have proved that the combination of breast cancer cell CXCR4 and its ligand CXCL12 can promote the proliferation of primary tumor and distant metastasis of liver, lung, and brain, which will aggravate the patient's condition and increase the difficulty of treatment." (PMID 35979048, 2022). "The high expression of CXCR4 in 4 T1 breast cancer cells was widely demonstrated in much research." (PMID 35630915, 2022). "Another study demonstrated that B cells could enhance the metastatic ability of breast cancer cells by activating the CXCR4/SDF1α axis in tumor cells via secreting HSPA4-targeting immunoglobins." (PMID 36046337, 2022). "Our study confirms the important role of receptor CXCR4 on breast cancer cell growth and migration." (PMID 35111484, 2021). "CD44 is a cell surface adhesion molecule that mediates cell‐cell and cell‐extracellular matrix (ECM) interactions by binding to hyaluronic acid (HA), whilst CD24 is a small sugar involved in the negative regulation of chemokine receptor CXCR4 protein activity in mediating breast cancer metastasis." (PMID 33305893, 2021). "Based on these findings, it is rational to hypothesize that ETV4 facilitate SHH signaling activation by modulating CXCR4 expression in breast cancer." (PMID 34052833, 2021). "CXCR4 has been shown to be involved in tumor growth and metastasis of breast cancer." (PMID 34503103, 2021). "Finally, performing TCGA data mining and using human breast cancer patient samples, we demonstrate that expression of CXCR4 and DR5 are inversely regulated." (PMID 33966046, 2021). "For example, silencing the CXCR4 gene in the breast cancer cell line can significantly inhibit the growth of tumor cells, reduce colony formation, and increase the sensitivity of cisplatin chemotherapy, and CXCR4 gene silencing can significantly block the metastasis of breast cancer." (PMID 35111484, 2021). "Furthermore, this study, for the first time, revealed the important functional interplay of a purinergic receptor P2Y11 and a chemokine receptor, CXCR4, in mediating the effect of ATP in inhibiting breast cancer bone metastasis." (PMID 34503103, 2021). "Ginsenoside Rg3 suppresses progression of breast cancer by targeting CXCR4 expression." (PMID 34111025, 2021). "Moreover, nonhydrolyzable ATP derivatives can be potentially adopted as potential therapeutic agents that suppress CXCR4 and, consequently, breast cancer growth in the bone." (PMID 34503103, 2021). "Guo and co-workers found that NGAL siRNA-containing pH-dependent nanoliposomes coated with anti-CXCR-4 antibodies were delivered more efficiently and more specifically to metastatic breast cancer cell lines expressing high CXCR-4 levels respect to cell lines not expressing this chemokine receptor." (PMID 34830212, 2021). "Potential therapeutic strategies have been developing by targeting CXCR4 or its ligand using antibodies, small peptides, or small interfering RNAs (siRNAs), and efficacy has been shown in inhibiting primary tumor growth and metastasis of breast cancer." (PMID 34503103, 2021). "Many studies have focus on the role of CXCR4 expressed in breast cancer cells." (PMID 35111484, 2021). "As CXCR4-induced Akt phosphorylation upregulates VEGF expression in tumor metastasis by enhancing mesenchymal proteins, we explored the regulatory action of miR-139 on CXCR4/p-Akt axis with respect to stemness and invasiveness properties of breast cancer cell linking VEGF-mediated EMT." (PMID 34070538, 2021). "A functional interaction between the IGF1R and CXCR4 was documented in breast cancer cell lines where CXCR4 and IGF1R directly interacted at the cell membrane, thereby inducing IGF1-evoked CXCR4 transactivation and cell migration independently of its cognate ligand CXCL12." (PMID 34440844, 2021). "C-X-C chemokine receptor type 4 (CXCR4) is overexpressed on metastatic breast cancer cells." (PMID 33925129, 2021).